IL6 (interleukin 6)
Diseases named in the same sentence as IL6 in open-access papers (continued):
Sharing a sentence is not in itself a finding about the gene and the disease.
viral myocarditis (continued). "miR-155 is also up-regulated in viral myocarditis; where it is expressed by infiltrating immune cells, and seems to be involved in TNF-α, IFN-γ and IL-6 production, as well as immune cell infiltration." (PMID 36072583, 2022). "Subsequently, we learned intermolecular interactions of herbal components and their targeting heart-tissue-specific CHRM2, FABP3, TNNC1, TNNI3, TNNT2, and SCN5A and cardiac-myocytes-specific IL6, MMP1, and PLAT coupled with viral myocarditis." (PMID 34456633, 2021). "In contrast, overexpression of IL-6 significantly increases the expression of tumor necrosis factor α (TNF-α) and aggravates myocardial injury in viral myocarditis mice." (PMID 33099539, 2020). "In this study, we showed increased expression levels of proinflammatory cytokines (TNF-α, IL-6, and MCP-1) as well as antiviral cytokines (IFN-β and IFN-γ) and an anti-inflammatory cytokine (IL-10) due to viral myocarditis in cardiac tissue." (PMID 25374444, 2014). "Carvedilol increased the cardiac CREB expression and phosphorylation and decreased the plasma catecholamine levels and the production of IL-6 and TNF-α with amelioration of acute viral myocarditis." (PMID 24225056, 2013). "The expression and phosphorylation of CREB were decreased with concomitant increase of IL-6 and TNF-α in murine coxsackievirus-induced acute viral myocarditis." (PMID 24225056, 2013). "Second, carvedilol increased cardiac CREB expression and phosphorylation and decreased the plasma catecholamine levels and the production of IL-6 and TNF-α with amelioration of acute viral myocarditis." (PMID 24225056, 2013). "Importantly, gene sets related to the IL6-JAK-STAT3 signaling pathways, inflammatory response, and interferon response exhibited differential activation in viral myocarditis compared to the control group." (PMID 40230577, 2025). "Finally, nicotine treatment reduced inflammatory cytokines (IL-1β, IL-6, and TNF-α) in the myocardium, ameliorated the necrosis of cardiomyocytes and cellular infiltration in mice with viral myocarditis." (PMID 30176160, 2018). "We also inferred that in mice with viral myocarditis, methyllycaconitine blocked α7nAchR, decreasing the phosphorylation of STAT3; this resulted in the up-regulation of the expression of the cytokines TNF-α and IL-6 and aggravated the inflammatory response." (PMID 25396421, 2014). "Thus, we inferred that in mice with viral myocarditis, nicotine activated α7nAchR, increasing the phosphorylation STAT3; this resulted in the down-regulation of the expression of the cytokines TNF-α and IL-6 and relieved the inflammatory response." (PMID 25396421, 2014). "From this, we speculated that the cholinergic anti-inflammatory pathway did not affect the production and release of IFN-γ in viral myocarditis, the reduction in the inflammatory response was through the down-regulation of IL-1β, IL-6, and TNF-α, not IFN-γ." (PMID 28197102, 2017). "Similarly, in the chronic viral myocarditis model, we determined that over the course of the progression of viral myocarditis to DCM, the lack of IL-17A stimulation leads to the significant downregulation of IL-6." (PMID 23977238, 2013).
acute GVHD (26 papers, 2010 to 2026). "The PTCy alone regimen of GVHD prophylaxis, grade II-IV acute GVHD, and IL-6 levels were associated with NRM in the univariate analyses." (PMID 39812969, 2025). "Univariate analysis showed that non-CR1 status at transplantation, grade II-IV acute GVHD, and serum IL-6 levels were associated with poor OS." (PMID 39812969, 2025). "Early elevation of IL-6 levels has also been linked to acute GvHD whilst REG3a and Tim-3 have also been linked to gastrointestinal inflammation." (PMID 38235129, 2023). "G polymorphism at position 174 of the recipient IL6 gene was associated with a higher incidence of acute GVHD (GG vs. GC/CC; P = 0.024)." (PMID 34120222, 2022). "In multivariate analysis, we confirmed that IL6-174 and IL6-597 SNPs are independent significant risk factors for the occurrence of acute GVHD and chronic GVHD." (PMID 34120222, 2022). "Patients with IL6-597 GG genotype developed acute GVHD more frequently than individuals with an A allele (GG vs. GA vs. AA; P = 0.013)." (PMID 34120222, 2022). "We conclude that IL6-174 and IL6-597 SNPs of pediatric patients were significant risk factors for the development of acute GVHD and chronic GVHD." (PMID 34120222, 2022). "For both IL6 polymorphisms, recipients with GG genotype developed acute GVHD and chronic GVHD more frequently than individuals with C or A allele." (PMID 34120222, 2022). "In summary, for both IL6 polymorphisms a recipient GG genotype was associated with an increased risk of acute GVHD." (PMID 34120222, 2022). "In multivariate analysis, the IL6-174 and IL6-597 SNPs were independent significant risk factors for acute GVHD (P = 0.030; P = 0.007, respectively) as well as for chronic GVHD (P = 0.045; P = 0.015, respectively)." (PMID 34120222, 2022). "Our study identified the IL6-174 and IL6-597 GG genotypes of pediatric allogeneic HSCT recipients as genetic risk factors for the development of acute GVHD and chronic GVHD." (PMID 34120222, 2022). "Several studies also suggest that specific single nucleotide polymorphisms (SNP) in Interleukin-6 (IL-6) genes influence the risk and severity of acute GVHD." (PMID 27809289, 2016). "In the third stage, cellular and inflammatory factors are released, including TNF-α, IL-1, IL-6, IL-10, IL-12, which underlie the clinical manifestations of acute GVHD." (PMID 23802653, 2013). "Previous work has shown that IL-2, IL-6, TNF-α and IFN-γ secretion is associated with acute graft-versus-host disease, whilst increased circulatory levels of IL-6 have been associated with chronic graft-versus-host disease." (PMID 20718971, 2010). "Serum IL-6 levels were associated with grades II–IV acute GVHD (r = 0.547, p < 0.001)." (PMID 39812969, 2025). "The IL6-174 G allele is associated with a higher serum level of IL6 resulting in an increased inflammatory response and a higher risk to develop acute GVHD and chronic GVHD." (PMID 34120222, 2022). "These proinflammatory effects may also influence endothelial cells; this effect is reflected in the association between pretransplant IL6 systemic levels, early posttransplant fluid retention, and increased risk of acute GVHD, transplant-related mortality and overall survival." (PMID 32707721, 2020). "Elevated IL-6 levels are suspected to reduce Treg activity, ultimately resulting in increased severity of acute GVHD." (PMID 39812969, 2025). "CRS severity was correlated with IL-6 levels (r = 0.801, p < 0.001) and positively correlated with the degree of acute GVHD (p = 0.004)." (PMID 39812969, 2025). "Two cases of acute GVHD presented with skin pruritus and diarrhea, along with elevated levels of IL-6, IL-8, and elafin." (PMID 38438967, 2024). "It has been reported that conditioning regimens lead to host tissue damage and elevated levels of inflammatory cytokines, including IL-6, which is important in the initiation phase of acute GVHD pathophysiology." (PMID 37626859, 2023).
acute GVHD (continued). "We observed that patients with the IL6-174 GG genotype developed acute GVHD (grade II–IV) more frequently than individuals with the C allele." (PMID 34120222, 2022). "Our study showed that IL-6 responsiveness remains higher in patients with previous acute GVHD, with a subset of patients showing significantly high IL-6 responsiveness following GVHD." (PMID 35566660, 2022). "Severe acute GVHD (grade III–IV) was significantly more frequent in patients with IL6-597 GG genotype than in those with IL6-597 GA/AA genotype (GG vs. GA/AA; P = 0.042)." (PMID 34120222, 2022). "We observed a significantly increased incidence of moderate to severe acute GVHD (grade II–IV) in recipients with IL6-174 GG genotype compared to those with IL6-174 GC/CC genotype (GG vs. GC/CC; P = 0.024)." (PMID 34120222, 2022). "Overall, this study further confirmed a role for IL-6 in acute GVHD pathophysiology in the GI tract." (PMID 34899738, 2021). "Rates of grades III–IV acute GvHD were higher in patients with post-transplant IL6 levels higher than 16.5 pg/ml (19 vs. 4%; p = 0.05)." (PMID 31632401, 2019). "Treatment of cells with UA prior to allogenic transplantation significantly delayed induction of acute graft-versus-host disease in mice and also significantly reduced the serum levels of pro-inflammatory cytokines IL-6 and IFN-γ." (PMID 22363615, 2012). "IL-6 levels increased concurrently with the severity of acute GVHD (r = 0.547, p < 0.001)." (PMID 39812969, 2025). "We recently demonstrated that classical IL-6 signaling by donor T cells is the predominant pathway in GVHD pathogenesis, and inhibition of IL-6 signaling with the IL-6R monoclonal antibody tocilizumab has shown activity in the prevention of acute GVHD in clinical studies." (PMID 38557487, 2024). "Importantly, the clinical importance of proteomic biomarkers can extend beyond prognostic value as antibody-mediated blockade of ST2 or IL-6 has shown value in reducing the incidence of subsequent acute GvHD." (PMID 38235129, 2023). "Serum IL-6 levels measured pre-conditioning and one week after transplant were predictive of acute GVHD and transplant-related mortality, although, the pleiotropic nature of IL-6 may be a concern." (PMID 36817455, 2023). "High levels of IL6 correlate with the manifestation, the severity, and the prognosis of acute GVHD." (PMID 34120222, 2022). "It should also be emphasized that IL-6 is not only important for immunoregulation; several organs depend on IL-6 for tissue renewal and regeneration, especially the liver and gut, which are target organs in acute GVHD." (PMID 35566660, 2022). "However the effects of STAT3 activation are difficult to predict, and additional studies are needed to clarify the molecular mechanisms behind and the functional effects of the altered/increased IL-6 responsiveness in patients with previous acute GVHD." (PMID 35566660, 2022). "In addition to the occurrence of acute GVHD and chronic GVHD, we investigated the influence of the IL6-174 and IL6-597 polymorphisms on OS, EFS, RI, and TRM." (PMID 34120222, 2022). "Furthermore, animal studies suggest that a primary effect of IL-6 in acute GVHD is enhanced differentiation of pro-inflammatory T cell subsets (Th1 and Th17 cells) together with reduced development of regulatory T cells (Tregs)." (PMID 35566660, 2022). "Furthermore, the IL6-597 SNP of the recipients turned out to be an independent significant prognostic factor for acute GVHD (P = 0.007) and chronic GVHD (P = 0.015)." (PMID 34120222, 2022). "Furthermore, patients with IL6-597 GG genotype developed grade II–IV acute GVHD more frequently than individuals with the GA or AA genotype (GG vs. GA vs. AA; P = 0.013)." (PMID 34120222, 2022). "However, the IL-6 effects varied between patients and were at least partly associated with both previous ATG prophylaxis and previous acute GVHD." (PMID 35566660, 2022). "Recently, the role of IL-6 during the pathophysiology of acute GVHD was further defined." (PMID 34899738, 2021).
acute GVHD (continued). "Notably, high pro-inflammatory cytokine levels of IL-6 correlate with decreased acute GVHD survival in the mice." (PMID 34707616, 2021). "A high level of cytokine IL-6, produced by almost all cells in response to any type of simulation, may be an early predictor of acute GVHD." (PMID 33384597, 2020). "Further, increases in several cytokines could trigger kidney injury in acute GVHD; when acute GVHD occurred, interleukin (IL)-2, IL-6, or tumor necrosis factor-α was upregulated in the kidney." (PMID 30842899, 2019). "IL-6 is also considered a potential biomarker of acute GVHD after allogeneic HSCT, and elevated IL-6 levels have been shown to be significantly associated with worse outcomes, including severe cytokine release syndrome (CRS) and acute GVHD, and decreased overall survival." (PMID 40141165, 2025). "Furthermore, in our study, IL-6 was the only predictor of survival and treatment-related mortality, suggesting that IL-6 measurements after haplo-HSCT with PTCy may be useful for predicting both acute GVHD and post-transplant prognosis." (PMID 39812969, 2025). "Among the studied cytokines, IL-6 is already being considered as a potential biomarker for acute GVHD following allogenic HSCT, where elevated IL-6 levels were significantly associated with worsening outcomes, including severe CRS, acute GVHD, and reduced overall survival." (PMID 37626859, 2023). "While our data are in agreement with most previous studies which suggest a relationship between the IL6-174 GG genotype of the recipients and an increased risk for development of acute GVHD, other authors did not observe an association between IL6-174 SNP and acute GVHD." (PMID 34120222, 2022). "To investigate a possible association between recipients’ and donors’ IL6-174 and IL6-597 SNPs and the occurrence of acute GVHD, we compared the proportion of genotypes between recipients with clinically significant acute GVHD (grade II–IV) and severe acute GVHD (grade III–IV)." (PMID 34120222, 2022). "In contrast, elevated IL-6, IL-17A, PAI-1, IL-10, CX3CL1, CXCL1, and CCL4 levels were prognostic for quiescent cGVHD compared with patients with resolved acute GVHD only." (PMID 41798937, 2026). "In this study, we demonstrated that the addition of ATG to PTCy reduced post-transplant IL-6 levels, contributing to a lower severity of CRS and acute GVHD after haplo-HSCT, thereby improving survival outcomes." (PMID 39812969, 2025). "The addition of ATG before stem cell infusion affected IL-6 levels and reduced the incidences of CRS and grade II–IV acute GVHD in haplo-HSCT patients." (PMID 39812969, 2025). "In conclusion, the addition of ATG to PTCy decreased IL-6 levels; reduced the incidence of CRS, acute GVHD, and NRM; and improved OS." (PMID 39812969, 2025). "IL6 targeting is also used in the treatment of GVHD; JA2 inhibition is used in the treatment of acute GVHD and this represents inhibition of JAK2-STAT3 signaling that is the main intracellular pathway downstream to the IL6Rα-gp130 receptor." (PMID 32707721, 2020). "IL-6 can also promote the differentiation of Th17 T cells, important regulators of autoimmune responses, which occur in DED and acute GvHD." (PMID 22509110, 2012). "Cytokines have been suggested to play a major role in development of systemic and ocular GvHD and increased levels of interleukin (IL)-6 and interferon gamma (IFN-γ) have been observed in serum in patients with systemic acute GvHD." (PMID 22509110, 2012). "Prevention of acute GVHD by SD-36 treatment of WT T cells was associated with lower serum concentrations of IFN-γ, TNF-α, and IL-6, but not IL-2, and was confirmed by histopathology." (PMID 37526084, 2023). "We compared the IL-6 responsiveness for patients with and without previous acute GVHD when anti-CD3+anti-CD28 was present during IL-6 stimulation." (PMID 35566660, 2022).
acute GVHD (continued). "Two studies suggest that combination of IL-6 blockade with standard GVHD prophylaxis reduces the rate of severe acute GVHD without increasing the rates of complications." (PMID 35566660, 2022). "Documented IL-6 signaling is critical to induce donor type-17 T (Th17) and type 22 T (Th22) cell differentiation after bone marrow transplantation (BMT), and the anti-IL-6 receptor monoclonal antibody, tocilizumab, has been shown to effectively reduce the incidence of acute GVHD." (PMID 39328417, 2024). "Thus, early post-transplant CD3+CD4+ and CD3+ CD8+ T cell subsets differ in their IL-6 responsiveness; this responsiveness is modulated by antithymocyte globulin and differs between patients with and without previous acute GVHD." (PMID 35566660, 2022). "Thus, post-transplant T cells derived from patients with and without previous acute GVHD show similar STAT3 (Tyr727) phosphoresponses to IL-6, whereas STAT3 (Ser727) and mTOR (Ser2448) responses differ between the two patient subsets." (PMID 35566660, 2022). "We compared the IL-6 phosphoresponses for patients with and without previous acute GVHD." (PMID 35566660, 2022). "Third, we observed differences in IL-6 responsiveness between patients with and without previous acute GVHD; it cannot be judged from our present data whether these differences reflect differences predisposing to or induced by the previous acute GVHD." (PMID 35566660, 2022). "Thus, activated CD3+CD8+ T cells showed no major differences in IL-6 responsiveness when comparing patients with and without previous acute GVHD; this is in contrast to the CD3+CD4+ T cell subset that differed in STAT (Ser727) and mTOR (Ser2448) responses between the two patient subsets." (PMID 35566660, 2022). "This IL-6 responsiveness is modulated by ATG, and the responsiveness differs between patients with and without previous acute GVHD." (PMID 35566660, 2022). "Even though we did not perform a detailed study of IL-6 responsiveness in various CD4+/CD8+ T cell subsets, it seems justified to conclude that post-transplant circulating CD4+ and CD8+ T cells derived from patients with and without previous acute GVHD differ in their IL-6 responsiveness." (PMID 35566660, 2022). "Thus, although IL-6 exposure has relatively weak effects on circulating CD3− mononuclear cells derived from allotransplant recipients, there is a difference between patients with and without previous acute GVHD also for these cells." (PMID 35566660, 2022). "The disadvantage of investigating IL-6 responsiveness at day +90 is that some patients develop late acute GVHD during a further reduction in immunosuppression; analysis of samples collected at this time point thus captures most, but not all, patients developing acute GVHD." (PMID 35566660, 2022).